LRG1 (leucine rich alpha-2-glycoprotein 1)
Diseases named in the same sentence as LRG1 in open-access papers (continued):
Sharing a sentence is not in itself a finding about the gene and the disease.
tumor (continued). "Here, LRG-1 stimulates an aberrant vessel growth by modulating pericyte–endothelial cell interactions; a process that fuels the establishment of a tumor-supporting microenvironment." (PMID 38413424, 2024). "LRG1 contributes directly to tumor cell viability and proliferation, promoting epithelial-to-mesenchymal transition and promoting dysfunctional angiogenesis." (PMID 37089863, 2023). "To further verify the ELK4‐LRG1 regulatory axis in vivo, we examined the expression of LRG1 in tumor tissues derived from wild‐type and Elk4−/− mice and from ELK4 OE/KD xenograft tumors." (PMID 37786278, 2023). "ELK4 cooperates with SP1 and SP3 instead of SRF to transcriptionally regulate LRG1, among others, to promote tumor angiogenesis, tumor growth, and metastasis." (PMID 37786278, 2023). "The leucine-rich alpha-2-glycoprotein 1 destabilizes tumor vessels and restricts immunotherapeutic potency." (PMID 37388743, 2023). "Overexpression of LRG1 dramatically restored tumor growth after U0126/MMA cotreatment, which suggested that synergistic downregulation of LRG1 mediated the antitumor effect of combination treatment." (PMID 37786278, 2023). "LRG1 would be complementary to information on intrinsic tumor factors provided by genomic tests, which are now endorsed by guidelines." (PMID 36353660, 2022). "In a recent landmark study, LRG1 has also been proposed as a major contributor to the metastatic niche, being synthesized by distant-organ endothelial cells in response to primary tumour-induced systemic inflammation." (PMID 35062948, 2022). "In response to various inflammatory stimuli, including injury, infections, autoimmune conditions, and tumour growth, both liver and tissue lesions contribute to LRG1 blood levels." (PMID 35062948, 2022). "LRG1 is a secreted glycoprotein that mediates the interaction between proteins and has been studied as a tumor-promoting factor that participates in signal transduction, cell proliferation, migration, invasion, adhesion, survival, and apoptosis." (PMID 36276281, 2022). "A reduced dissemination of mouse melanoma cells was also observed in Lrg1−/− mice further demonstrating a key role for LRG1 in tumour metastasis." (PMID 35062948, 2022). "Immunohistochemical detection of LRG1 in tissue sections has also shown that local tumour expression correlates with disease progression and patient survival." (PMID 35062948, 2022). "It is likely, therefore, that the high LRG1 expression levels observed in tumour endothelium are also driven by IL-6 and result in the subsequent disruption of endothelial-mural cell associations and consequential abnormal vascularisation." (PMID 35318338, 2022). "Our previous work has shown that in neovascular complications of the retina, Lrg1 expression is restricted to the neovascular endothelial cells, and in LRG1-negative tumours its expression is restricted to the tumour neovascular endothelial cells." (PMID 35318338, 2022). "Several in vitro studies suggest that LRG1 acts directly on tumour cells enhancing their viability, proliferation, and invasive properties." (PMID 35062948, 2022). "Leucine-rich alpha-2-glycoprotein 1 (LRG1) is present abundantly in the microenvironment of many tumours where it contributes to vascular dysfunction, which impedes the delivery of therapeutics." (PMID 34458833, 2021). "In our study, we aimed to evaluate diagnostic performances of traditional CRC tumor markers (CEA, CA19.9) vs LRG1 and SCF for early CRC diagnosis and assess its potential usefulness for monitoring CRC patient’s treatment." (PMID 33492603, 2021). "Since then, accumulating studies have focused on unveiling the potential roles of LRG1 in regulating tumor progression." (PMID 34930899, 2021). "Stattic, a Stat3 inhibitor, completely abolishes the promoting effects of LRG1 on tumour cell activation." (PMID 34208965, 2021).
tumor (continued). "Concomitant with this observation, haematoxylin-eosin staining of excised lungs showed a similar reduction in the percentage of tumour nodule area in the lungs of Lrg1-/- mice following the histopathological analysis." (PMID 34208965, 2021). "LRG1 expression was positively correlated with tumor size, metastasis, invasion, and higher expression of the essential prognostic factor-CEA which also predicted worse clinical outcomes." (PMID 34930899, 2021). "Recently, LRG1 is identified as a novel pro-angiogenic factor that contributes to tumor-growth and diabetic retinopathy." (PMID 32982792, 2020). "CLEC3B, KLKB1, and LRG1 displayed significant difference at RNA level among the tumor stages and patient survival time." (PMID 32545216, 2020). "On the contrary, the tumor burden in nude mice injected with LRG-1 knockdown cells was significantly lower than that in control mice." (PMID 30760292, 2019). "On the other hand, xenograft assays showed that the tumor burden in the nude mice injected with LRG-1 over-expressing PDAC cells was heavier than that in the nude mice injected with control cells." (PMID 30760292, 2019). "Our data showed that high LRG-1 expression (P = 0.001), late tumor stage (P < 0.001), and CA 19–9 levels (P = 0.020) were significant independent prognostic factors." (PMID 30760292, 2019). "The expression of LRG-1 in PDAC tissue was significantly higher than that in adjacent normal tissue, and high LRG-1 expression predicted poor survival and aan dvanced tumor stage." (PMID 30760292, 2019). "As proliferation play an important role in the carcinogenesis of tumours, and the cell cycle of eukaryotic cells is the essential process of cell proliferation, we investigated the role of LRG1 in the proliferation and the cell cycle of CRC cells." (PMID 28376129, 2017). "Based on our mass spectrometry data, A1BG and LRG1 were among the most markedly up-regulated proteins in the urine samples from tumor-bearing mice." (PMID 26133466, 2015). "In the training cohort, high LRG1 expression was more likely to present advanced clinical characters, including higher advanced clinical stage (P = 0.008), tumor size (P = 0.037) and worse tumor differentiation (P = 0.030)." (PMID 26517349, 2015). "Univariate analysis showed higher levels of LRG1 in the circulation of subjects with larger tumors, pointing toward a specific protein secretion from the tumor (small versus medium tumors: P = 5.7e-2; medium versus large tumors: P = 7.7e-4, Fig3D)." (PMID 26253081, 2015). "A minor protein band of ~34-36 kD, which corresponds to the predicted size of unmodified LRG1, was observed in several of the tumor and normal ovary samples." (PMID 20831812, 2010). "We have found that serum LRG1 levels appear to be more directly related to tumor burden compared to CA125." (PMID 20831812, 2010). "Our observation that LRG1 affects endothelial junctional molecule expression is also consistent with a reduction in NG2 expression, as NG2 has been shown to enhance junction formation, and promote the expression of CD31 in tumour-associated vessels." (PMID 40277918, 2025). "Indeed, in metastasis models the STAT3 signaling pathway has been shown to mediate LRG1-driven tumor metastasis, and that this can be significantly reduced in Lrg1 deficient mice or following LRG1 antibody blockade." (PMID 38745756, 2024). "Exosomes have a crucial function in facilitating the spread of metastatic castration-resistant prostate cancer (CRPC) by transporting proteins such as APOE, LRG1, and ITIH that are directly implicated in tumor growth and the formation of secondary tumors in the bones." (PMID 39187523, 2024). "Since ccRCC is a hypervascular tumor and LRG1 is capable of accelerating angiogenesis, we hypothesized that the LRG1 levels may be related to ccRCC." (PMID 38658967, 2024).
tumor (continued). "Further studies, however, will be required to determine whether Lrg1 induction in co-opted vessels exerts similar vasculopathic effects as observed in angiogenic tumor vessels and in vessels of other diseases." (PMID 38745756, 2024). "Since ccRCC is a hypervascular tumor and LRG1 is capable of accelerating angiogenesis, we hypothesized that LRG1 levels may be related to ccRCC." (PMID 38658967, 2024). "Interestingly, using similar tumor models it has been shown that the primary tumor induces systemic vascular LRG1 expression and that this primes the vascular metastatic niche and promotes tumor metastasis." (PMID 38745756, 2024). "The potential of LRG1 as a tumor biomarker has also been demonstrated in other studies." (PMID 38735538, 2024). "Unpublished data from our lab show that in addition to the vascular normalization effects, inhibition of LRG1 also promotes tumor infiltration of T-cells by modulating the immunosuppressive tumor microenvironment, thereby supporting a switch from being immunologically “cold” to “hot”." (PMID 38745756, 2024). "Of note, tumor cells of varying malignancies are able to express and secrete LRG-1." (PMID 38413424, 2024). "However, neutrophils in the gem group expressed high levels of CXCR2, LRG1, and LCN2 genes, which are associated with tumor progression and metastasis." (PMID 37324492, 2023). "Interestingly, anti-LRG1 antibody treatment showed efficacy in prolonging overall survival of mice injected with LLC cells which is amongst the tumour models that show a poor response to VEGF blockade." (PMID 34987199, 2022). "Indeed, as LRG1 has been described as a modifier of TGFβ signalling, this raises many questions over its potential role in tumour progression." (PMID 35062948, 2022). "In CRC, for example, LRG1 has been shown to inhibit apoptosis and modulate the EMT of tumour cells through expression of the transcription factors RUNX1 and HIF-1α, whose association with TGFβ and contribution to tumour growth are well-established." (PMID 35062948, 2022). "Moreover, LRG1 has been described as a powerful complementary marker to differentiate early-stage tumours from benign lesions and healthy controls." (PMID 35062948, 2022). "Indeed, we observed in a number of mouse tumour models that knockout of the Lrg1 gene, or its inhibition through a function-blocking antibody, delayed tumour growth and increased animal survival." (PMID 35062948, 2022). "Nevertheless, it raises the possibility that LRG1 may favour tumour aggressiveness through promotion of various TGFβ pro-oncogenic functions." (PMID 35062948, 2022). "Moreover, in the absence or inhibition of LRG1, the tumour vasculature exhibited enhanced pericyte coverage and improved function suggesting that LRG1 prevents mature vessels from forming in the TME." (PMID 35062948, 2022). "Outside tumors of the digestive system, LRG1 was found to be the biomarker in other tumor diseases." (PMID 35095520, 2021). "Furthermore, both tumour cell and endothelial cell-derived LRG1 were important for tumour cell extravasation." (PMID 34208965, 2021). "LRG1 regulates tumour angiogenesis by inducing VEGFA through HIF1α activation." (PMID 34208965, 2021). "It would be of interest to determine whether TGF-βwould be a prerequisite for LRG1 to exert its pro-metastatic function since TGF-βwas usually constitutively produced in the tumor milieu." (PMID 34930899, 2021). "LRG1 is present abundantly in the microenvironment of many tumours." (PMID 34458833, 2021). "Despite the important role of LRG1 in angiogenesis, there was no change in tumour angiogenesis and tumour growth in Lrg1-deficient mice." (PMID 34208965, 2021). "Thus, further studies are warranted to determine the exact role of LRG1 in tumor progression in a context-dependent manner." (PMID 34930899, 2021).
tumor (continued). "To exclude the possible inaccurate conclusion due to hepatocytes contamination in the metastatic tumor specimens, we performed IHC staining of LRG1 and confirmed that tumor cells are the major component which expressed a comparable level of LRG1 to hepatocytes." (PMID 34930899, 2021). "Together, these data suggest that host Lrg1-deficiency does not affect tumour cell viability, proliferation, and tumour angiogenesis." (PMID 34208965, 2021). "Considering the role of LRG1 in ocular angiogenesis, we next investigated whether tumour vascularization is affected in wild-type and Lrg1-/- mice." (PMID 34208965, 2021). "What is the mechanism by which overexpressed LRG1 participates in tumor progression?" (PMID 32337221, 2020). "Nevertheless, our data suggest that LRG1 might play multiple roles in tumor formation and metastasis of ESCC." (PMID 32047555, 2020). "However, there are also studies showing that LRG1 expression is down-regulated in tumors, inhibiting tumor cell proliferation while promoting apoptosis 18,19." (PMID 32047555, 2020). "The urine protein levels of LRG1 were higher in patients with AOSD than in patients with RA or neoplasms and HC subjects, and the urine protein levels of ORM1 and ORM2 in AOSD patients were dramatically higher than those in patients with RA, neoplasms, or infections and HC subjects." (PMID 33013889, 2020). "Moreover, the downregulation of LRG-1 also reduced the expression of critical factors participating in tumor metastasis, including MMP-2 and MMP-9." (PMID 30760292, 2019). "High expression levels of LRG1 were detected in 190 (60.9%) tumor specimens." (PMID 29029535, 2017). "In contrast, 122 (39.1%) tumor tissues expressed low levels of LRG1." (PMID 29029535, 2017). "Elevated expression of LRG1 was frequently accompanied with worse malignant phenomenon, such as larger tumor size, more advanced tumor stage, poorer tumor differentiation and more vascular invasion in a large cohort of 777 HCC cases (In Zhang's study, only 51 HCC samples were collected)." (PMID 26517349, 2015). "In the overall cohort, patients with high LRG1 expression was accompanied with higher advanced clinical stage (P = 0.010), larger tumor size (P = 0.004), more vascular invasion (P = 0.019) and worse tumor differentiation (P < 0.001)." (PMID 26517349, 2015). "In our study, LRG1 expression was frequently higher in HCC patients with larger size tumor and advanced stage, which indicate that LRG1 might be capable of interfering with the development of HCC." (PMID 26517349, 2015). "The production and secretion of LRG1 by tumor cells suggests there may be a more direct relationship between tumor burden and serum levels of LRG1 than for other acute phase proteins secreted only by the liver." (PMID 20831812, 2010). "Our observations may suggest a tumor-promoting role of LRG-1 in early BC." (PMID 38413424, 2024). "However, it remains to be shown whether cellular LRG-1 expression changes at different stages of the primary tumor, by metastatic spread or by local changes of the immune signature in BC." (PMID 38413424, 2024). "Importantly, they could also demonstrate that downregulation of LRG1 via silencing of nuclear paraspeckle assembly transcript 1 (NEAT1) can prevent tumour cell migration and invasion." (PMID 34987199, 2022). "It was recently discovered that LRG1 may play an important role in tumour survival in RB." (PMID 34987199, 2022). "Recent advances in the interpretation of the molecular mechanism of LRG1 in tumor indicated that long noncoding RNA taurine upregulated one mediated endothelial angiogenesis through the LRG1/TGF-β pathway, which could predict clinical outcomes after transarterial chemoembolization." (PMID 35095520, 2021). "Down-regulation of LRG1 in ESCC patients may favor tumor metastasis and disease progression." (PMID 32047555, 2020). "Decreased expression of LRG1 in ESCC might favor tumor growth due to reduced apoptosis." (PMID 32047555, 2020).
tumor (continued). "Furthermore, multivariate Cox proportional hazards regression analysis indicated that the age, TNM stage, differentiation grade, surgical margin, vascular invasion, tumor location and LRG1 expression level were independent prognostic factors of OS in this study." (PMID 29029535, 2017). "LRG1 interacts with OLFM4 to activate EMT and angiogenesis, enhancing MM cell proliferation, tumor invasiveness, and vascular formation." (PMID 40303340, 2025). "Inverse correlations were found between the IHC scores of PROS1 (P = .024), CLU (P = .010), and LRG1 (P = .038) and PTC patients with higher tumor classification, respectively." (PMID 40797389, 2025). "Like LRG1, CSF1 is also important in regulating redundant inflammation in the tumor microenvironment and in achieving timely wound healing after chemical and physical insult." (PMID 38386171, 2024). "Deletion or antibody-based neutralization of Lrg1 results in vessel normalization and promotes the TME toward an anti-tumor, immune-active state, enhancing the efficacy of various cancer therapies." (PMID 38580870, 2024). "HIF-1α knockdown was shown to block LRG1-mediated angiogenesis, EMT, and tumor invasiveness, and is consistent with LRG1 being induced in response to hypoxia." (PMID 38745756, 2024). "Another study looking at blood biomarkers with an impact on GBM biology found that leucine-rich alpha-2-glycoprotein (LRG1), C-reactive protein (CRP), and complement component C9 (C9) were correlated with tumor size." (PMID 39057054, 2024). "Regarding the roles of intracellular LRG1, several studies revealed that LRG1 regulates the TGF-β signalling pathway, serving a crucial role in tumor development." (PMID 38658967, 2024). "Of note, we also observed a positive correlation between the tumor vasculature marker CD31 and the protein levels of LRG1, ELK4, SP1 and SP3 in our CRC cohort." (PMID 37786278, 2023). "Collectively, our data demonstrate that LRG1 is transcriptionally regulated by the ELK4‐SP1/3 complex and is required for the oncogenic function of the ELK4‐SP1/3 complex, especially in tumor angiogenesis." (PMID 37786278, 2023). "Among them, leucine-rich alpha-2-glycoprotein (LRG1), complement component C9 (C9), and C-reactive protein (CRP) showed significant positive correlations with tumor size." (PMID 35806478, 2022). "In the tumour microenvironment (TME) stromal cells, including endothelial and myeloid cells, also contribute to LRG1 production." (PMID 35062948, 2022). "Mechanistically, LRG1 exerts its function by regulating EGFR/STAT3 signalling, a central pathway involved in tumour metastasis." (PMID 34208965, 2021). "We show that the extracellular LRG1-targeting ADC provides an increase in survival in vivo when compared against antibody alone and similar anti-tumour activity when compared against standard chemotherapy, but without undesired side-effects." (PMID 34458833, 2021). "Levels of routine biochemical and hematological markers, traditional tumor markers (CA19.9 and CEA), and candidate markers (LRG1 and SCF) were determined." (PMID 33492603, 2021). "Another molecule Lrg1, a mitogen demonstrated to promote angiogenesis in the presence of TGF-β1, was highly expressed in tumor ECs and upregulated in adjacent normal ECs." (PMID 32440964, 2020). "The expression of LRG-1 in PDAC tissue was significantly higher than that in adjacent normal tissue, and high LRG-1 expression predicted poor survival and a late tumor stage." (PMID 30760292, 2019). "LRG-1 remarkably promoted the viability, proliferation, migration and invasion of PDAC cells and facilitated tumor growth in vivo." (PMID 30760292, 2019). "Pearson correlation analysis showed a significant positive correlation between plasma protein concentrations and tumor size for CRP, C9, and LRG1." (PMID 29513714, 2018). "The plasma concentrations of LRG1, CRP, and C9 showed significant positive correlations with tumor size (R2 = 0.534, 0.495, and 0.452, respectively)." (PMID 29513714, 2018).